EPHA5 (EPH receptor A5)
Diseases named in the same sentence as EPHA5 in open-access papers (continued):
Sharing a sentence is not in itself a finding about the gene and the disease.
EPHA5 also shares sentences with these, for which no sentence is quoted: dementia (3 papers); lung squamous cell carcinomas (2); migraine (2); non-small cell lung carcinoma (2); pancreatic cancer (2); acute lymphoblastic leukemia (1); adenocarcinoma (1); angiosarcoma (1); Anxiety (1); astrocytomas (1); B-cell lymphoma (1); benign ovarian neoplasms (1); bladder cancer (1); breast tumor (1); corticotropic adenomas (1); diabetes (1); esophageal adenocarcinoma (1); Hyperglycemia (1); insulinoma (1); liver fibrosis (1); metastatic disease (1); myocardial infarction (1); neuroendocrine neoplasm (1); nevus (1); Obesity (1); ovarian serous borderline tumors (1); papillary renal cell carcinoma (1); prolactinoma (1); renal carcinoma (1); renal cell carcinoma (1).
A further 6 diseases each share a sentence with EPHA5 in 1 paper.